TACC2 (transforming acidic coiled-coil containing protein 2)
Description:
Plays a role in the microtubule-dependent coupling of the nucleus and the centrosome. Involved in the processes that regulate centrosome-mediated interkinetic nuclear migration (INM) of neural progenitors (By similarity). May play a role in organizing centrosomal microtubules. May act as a tumor suppressor protein. May represent a tumor progression marker.
Synonyms: AZU-1; ECTACC
Tractability: Antibody: its Gene Ontology location is reachable by antibodies, with high confidence. PROTAC: ubiquitination databases record sites on it; its protein half-life has been measured.
Gene: Protein-coding gene on chromosome 10 (121,989,163 to 122,254,545, forward strand). Ensembl gene ENSG00000138162.
Subcellular location: Cytoplasm; Nucleus; Cytoplasm, cytoskeleton, microtubule organizing center, centrosome
Subcellular location (Human Protein Atlas): Cytosol; Nucleoplasm; Plasma membrane
Gene Ontology:
Molecular function: nuclear receptor binding
Biological process: astral microtubule organization; cerebral cortex development; nuclear migration; mitotic spindle organization
Cellular component: cytoplasm; cytosol; nucleoplasm; nucleus; centrosome
Genetic constraint (gnomAD): Loss-of-function variants: 135 observed, 235.26 expected, observed/expected ratio (o/e) 0.57, 90% interval 0.5 to 0.66. The upper end of that interval is the gene's LOEUF score, 0.66, which puts it in group 2 of 6, group 1 being the genes least tolerant of losing a copy. Missense variants: 3,466 observed, 3,860.4 expected, observed/expected ratio (o/e) 0.9, 90% interval 0.87 to 0.92. Synonymous variants: 1,521 observed, 1,553.9 expected, observed/expected ratio (o/e) 0.98, 90% interval 0.94 to 1.02.
Homologues: Orthologues: macaque TACC2 (90% identical), dog TACC2 (67% identical), mouse Tacc2 (60% identical), rat Tacc2 (58% identical), chimpanzee TACC2 (37% identical), guinea pig Tacc2 (32% identical), pig TACC2 (31% identical), tropical clawed frog tacc2 (29% identical), Drosophila melanogaster tacc (7% identical). Paralogues in human: TACC1 (11% identical), TACC3 (8% identical).
Diseases named in the same sentence as TACC2 in open-access papers:
TACC2 is named in the same sentence as 45 diseases in open-access papers, as found by Europe PMC text mining. Sharing a sentence is not in itself a finding about the gene and the disease. The quoted sentences say what the papers report.
breast cancer (19 papers, 2005 to 2025). A primary or metastatic malignant neoplasm involving the breast. "Variants at the TACC2 locus are associated with risk of low-grade breast cancer, overall breast cancer, and epithelial ovarian cancer." (PMID 38836758, 2024). "Specifically, the SNP which had the highest iHS and nSL scores was SNP rs11599686 (chr10:123863188), located in the TACC2 gene associated with the susceptibility of complex diseases such as breast cancer." (PMID 34616433, 2021). "Among this short list, GADD45A, TANK and TACC2 are already known risk related factor in breast cancer." (PMID 28621677, 2017). "TACC2 status was significantly associated with an increased incidence of recurrence in breast cancer patients (P = 0.0009 by log‐rank test)." (PMID 27333920, 2016). "In this study, TACC2 status was significantly associated with recurrence and worse prognosis of female breast cancer cases, and a similar tendency was also shown in the cases which received adjuvant endocrine therapy and/or chemotherapy." (PMID 27333920, 2016). "On the other hand, single‐nucleotide polymorphisms (SNPs) in TACC2 were significantly associated with a risk of low‐grade breast cancer 25, and TACC2 mRNA expression was significantly correlated with shorter disease‐free survival of breast carcinomas patients." (PMID 27333920, 2016). "(2010) reported that high expression of TACC2 mRNA in tumor tissue was associated with shorter disease‐free survival of breast carcinoma patients by real‐time PCR analysis." (PMID 27333920, 2016). "In this study, immunoreactivity of TACC2 was positively associated with Ki‐67 LI in breast carcinomas." (PMID 27333920, 2016). "TACC2 immunoreactivity was detected in 78 out of 154 (51%) breast carcinoma tissues, and it was significantly associated with Ki‐67 LI." (PMID 27333920, 2016). "Moreover, TACC2 status was significantly associated with worse prognosis of the cases and it turned out an independent prognostic factor for both the disease‐free and breast cancer‐specific survival." (PMID 27333920, 2016). "TACC2 belongs to a conserved family of centrosome- and microtubule-interacting proteins and has been reported as a putative tumor suppressor in breast cancer." (PMID 39160538, 2024). "TACC2, an oncogene in breast cancer, is a member of the transforming acidic coiled-coil protein family." (PMID 34660294, 2021). "On the other hand, TACC2 has been demonstrated to promote androgen‐mediated growth in the prostate cancer 10, but previous evidences of TACC2 in breast cancer were inconsistent and its significance remains largely unclear." (PMID 27333920, 2016). "SNP rs79619171 in the FGFR2 region is a splice site donor in the TACC2 gene; it was observed only in the Japanese American samples (MAF 0.08) and was moderately associated with breast cancer (OR 1.47, 95 % CI 1.09–1.98, p = 0.01)." (PMID 27814745, 2016). "Further examinations are needed to clarify molecular regulatory mechanisms of TACC2 expression in breast carcinoma." (PMID 27333920, 2016). "This is a first study which demonstrates clinical significance of TACC2 immunoreactivity in breast carcinoma." (PMID 27333920, 2016). "In this study, immunoreactivity of TACC2 was detected in 51% of breast carcinoma, while it was negligible in morphologically normal mammary glands." (PMID 27333920, 2016). "Our present results demonstrated these findings, and it is suggested that TACC2 plays an important role in the cell proliferation of breast carcinoma." (PMID 27333920, 2016). "In summary, immunoreactivity of TACC2 was detected in 51% of breast carcinoma cells, and the TACC2 status was significantly correlated with Ki‐67 LI in these cases." (PMID 27333920, 2016). "MCF‐7 and MDA‐MB‐453 breast carcinoma cell lines were transfected with small interfering RNA (siRNA) for TACC2, and subsequently, cell proliferation, 5‐Bromo‐2′‐deoxyuridine (BrdU), and invasion assays were performed." (PMID 27333920, 2016).
breast cancer (continued). "Moreover, using multivariate analyses, we demonstrated that TACC2 status turned out an independent worse prognostic factor for both disease‐free and breast cancer‐specific survival." (PMID 27333920, 2016). "Mounting evidence suggests that TACCs is implicated in the progression of some human malignancies, but significance of TACC2 protein in breast carcinoma is still unknown." (PMID 27333920, 2016). "Therefore, TACC2 does not necessarily involve in AR signaling and other factors can be important in the regulation of TACC2 expression in the breast carcinoma, different from the prostate carcinoma." (PMID 27333920, 2016). "Therefore, in this study, we examined the clinical significance of TACC2 in breast carcinoma and biological functions by immunohistochemistry and in vitro experiments." (PMID 27333920, 2016). "Therefore, in our study, we examined TACC2 in breast carcinoma by immunohistochemistry and in vitro experiments to investigate its clinical significance and biological functions." (PMID 27333920, 2016). "“This suggests that increased TACC2 may mediate an oncogenic effect on breast cancer cells and indicates that TACC2 may be a potential therapeutic target”." (PMID 23216862, 2012). "TACC2 (AZU-1) is a putative tumor suppressor in breast cancer." (PMID 21113414, 2010). "In addition to the important functions in the process of mitosis, TACC2, one of fusion partners, has been identified as a tumor suppressor gene in breast cancer and hepatocellular carcinoma, the downregulation of which is an important step to drive tumorigenesis." (PMID 40615663, 2025). "Our present results suggest that immunoreactivity of TACC2 is increased in a subset of breast carcinoma compared to normal breast tissues, and the relatively wide distribution of immunoreactivity of TACC2 may also indicate biological importance of TACC2 in human breast carcinomas." (PMID 27333920, 2016). "Previous research has established a strong correlation between GAS41 and the breast cancer suppressor TACC, with GAS41 shown to interact with TACC1 and TACC2 of the TACC family." (PMID 37853482, 2023). "In contrast, TACC2 binds to and inhibits YEATS4 in breast cancer cell lines, attenuating tumor growth and migration." (PMID 37435030, 2023). "In order to further evaluate biological functions of TACC2 in human breast carcinoma cells, we transfected specific siRNA for TACC2 in MCF‐7 (ER+ and AR+) and MDA‐MB‐453 (ER‐ and AR+) breast carcinoma cells." (PMID 27333920, 2016). "A more recent study has indicated that TACC2 and TACC3 are members of a set of 21 proteins that are strong prognostic indicators of clinical outcome in breast cancer." (PMID 15918899, 2005). "Dysregulation of the human transforming acidic coiled-coil (TACC) protein is associated with the development and progression of breast cancer, where both TACC1 and TACC2 bind to YEATS4 to form complexes that affect the growth and proliferation of breast cancer cells." (PMID 37435030, 2023). "TACC2 immunoreactivity was detected in the cytoplasm of breast carcinoma cells, while it was negative in the morphologically normal glands or stroma." (PMID 27333920, 2016). "We previously identified 610 DHT‐induced genes in T‐47D breast carcinoma cells by microarray analysis 19, but TACC2 was not included in this list (data not shown)." (PMID 27333920, 2016). "However, in this study, we could not find significant association between TACC2 status and AR LI in breast carcinoma cases or induction of TACC2 mRNA expression by DHT treatment in breast carcinoma cells." (PMID 27333920, 2016).
gastric cancer (6 papers, 2002 to 2025). A primary or metastatic malignant neoplasm involving the stomach. "Interestingly, TACC1 and TACC2 have also have been detected by SEREX in gastric cancer by Yuichi Obata (SEREX database)." (PMID 12087473, 2002).
prostate carcinoma (6 papers, 2012 to 2025). A carcinoma that arises from epithelial cells of the prostate gland. "Additional variants were found in TACC2, a centrosomal protein important for mitotic spindle formation, and FRG1, a gene implicated in muscle and vascular development as well as prostate cancer." (PMID 41488087, 2025). "Functional AR‐binding sites were existed in the vicinity of TACC2 gene, and TACC2 expression was markedly induced by androgen in the prostate carcinoma cells." (PMID 27333920, 2016). "SNP in the TACC2 (rs3763763) is involved in ACM and prostate cancer-specific mortality." (PMID 37858151, 2023).
glioma (3 papers, 2010 to 2021). A benign or malignant brain and spinal cord tumor that arises from glial cells (astrocytes, oligodendrocytes, ependymal cells). "The interaction between PART1-hsa-mir-25-SLC12A5/TACC2/BSN/TLN2/ZDHHC8 is largely unclear in glioma and requires further analysis." (PMID 34660294, 2021). "SLC12A5/TACC2/BSN/TLN2/ZDHHC8 was downregulated in patients with glioma with poor OS." (PMID 34660294, 2021). "Conversely, TACC2 transcript levels were significantly downregulated in Grade IV gliomas." (PMID 21113414, 2010).
lymph node metastasis (3 papers, 2016 to 2021). "We have reported that activity of the intronic promoter p10 of TACC2 in primary lesion of endometrial cancer is indicative of lymph node metastasis among a low-risk patient group." (PMID 33931666, 2021).
breast tumor (2 papers, 2016 to 2024). "TACC2 encodes one of three homologous coiled-coiled proteins; it shows increased expression in higher grade breast tumors and is associated with local recurrence and reduced survival." (PMID 38836758, 2024). "TACC2 was identified as a putative breast tumor suppressor 11 and overexpression of TACC2 reverted a malignant phenotype to a benign phenotype 13." (PMID 27333920, 2016).
embryonal carcinoma (2 papers, 2022 to 2025). A non-seminomatous malignant germ cell tumor characterized by the presence of large germ cells with abundant cytoplasm resembling epithelial cells, geographic necrosis, high mitotic activity, and pseudoglandular and pseudopapillary structures formation. "A recent analysis of the Cancer Genome Atlas demonstrated that KIT, KRAS, and NRAS gene variants were observed only in seminoma, while gene variants in B3GNT8, CAPN7, FAT4, GRK1, TACC2, and TRAM1L1 occurred only in embryonal carcinoma." (PMID 41426877, 2025). "Mutations in ADAMTS20, ARHGAP10, OR1L4, PDS5A, and RPLP0 were only found in mixed germ cell tumors, while mutations in B3GNT8, CAPN7, FAT4, GRK1, TACC2 and TRAM1L1 were only observed in embryonal carcinoma, and their mutation frequency was around 2%." (PMID 36713456, 2022). "As described in our results, mutation that only occurs in embryonal carcinoma (B3GNT8, CAPN7, FAT4, GRK1, TACC2 and TRAM1L1) or seminoma (KIT, KARS and NRAS) may be valuable molecular markers and therapeutic targets that need to be considered clinically." (PMID 36713456, 2022). "Differences in somatic mutations between subtypes are also of concern, with our results suggesting that mutations in some genes (B3GNT8, CAPN7, FAT4, GRK1, TACC2, and TRAM1L1) occur only in embryonal carcinoma, while mutations in KIT, KARS, and NRAS are observed only in seminoma." (PMID 36713456, 2022).
endometrial cancer (2 papers, 2017 to 2021). Primary or metastatic malignant neoplasm involving the endometrium (mucous membrane that lines the endometrial cavity). "Next, we analyzed 16 cases of endometrial cancer and 5 normal endometria, as transcripts from the intronic promoter p10 of TACC2 were detectable in normal endometria at a similar level to lower cases of primary tumors." (PMID 33931666, 2021). "However, the role of TACC2 has never been elucidated in endometrial cancer, and the variety of its isoforms identified in this study has never been exploited in any context." (PMID 29074988, 2017).
chronic obstructive pulmonary disease (1 paper, 2022). A chronic and progressive lung disorder characterized by the loss of elasticity of the bronchial tree and the air sacs, destruction of the air sacs wall, thickening of the bronchial wall, and mucous accumulation in the bronchial tree. "Recently, compared with the smokers without chronic obstructive pulmonary disease (COPD), TACC2 protein levels were found to be reduced in the lung tissues of smokers with COPD." (PMID 35906197, 2022).
gastrointestinal stromal tumor (1 paper, 2025). "Recently, FGFR::TACC fusions have been reported in a variety of non-epithelial cancers, including FGFR1::TACC1 fusions as a novel alternative genetic driver in rhabdomyosarcoma, and FGFR2::TACC2 fusions as a mechanism of multidrug resistance in TKI-treated gastrointestinal stromal tumors (GIST)." (PMID 39387893, 2025).
invasive ductal carcinoma (1 paper, 2016). "Immunohistochemistry for TACC2 was performed in 154 cases of invasive ductal carcinoma." (PMID 27333920, 2016).
lentivirus infection (1 paper, 2025). Virus diseases caused by the Lentivirus genus. "We generated KYSE30 and KYSE150 cell lines stably expressing Flag-tagged PLEKHA1, TACC2, different PT fusion isoforms (Pe4Te20, Pe11Te17, Pe10Te23, Pe5Te17, and Pe2Te23) or an empty vector via lentivirus infection." (PMID 40615663, 2025).
myotonic dystrophy 1 (1 paper, 2024). "TACC2, encoding a cytoskeleton-related protein, is highly expressed in skeletal muscle, and is reported as a target of myotonic dystrophy 1-associated splicing alterations." (PMID 38769351, 2024).
ovarian carcinoma (1 paper, 2014). A malignant neoplasm originating from the surface ovarian epithelium. "Our data indicate TACC2 expression is increased by DEX in both OE-E6/E7 cells and primary FTE cells, which is consistent with a previous report showing increased expression of TACC2 by DEX in ovarian cancer cells." (PMID 24848801, 2014).
sarcopenia (1 paper, 2024). Progressive decline in muscle mass due to aging which results in decreased functional capacity of muscles. "Our findings would shed light on genetic components of lower limb muscle strength and indicate TACC2 as a potential therapeutic target for sarcopenia." (PMID 38769351, 2024). "Further studies would be necessary to clarify the role of TACC2 in muscle strength and sarcopenia." (PMID 38769351, 2024).
tumor (16 papers, 2010 to 2025). "Lack of TACC2 expression caused by PT fusion might have a potential role in PT positive tumor progression." (PMID 40615663, 2025). "The mouse models demonstrated that enforced TACC2 expression significantly enhanced the efficacy of PD-1 blockade, resulting in increased tumor suppression and survival." (PMID 41153795, 2025). "To validate the presence of predicted fusion proteins, we performed immunoprecipitation using an anti-TACC2 C-terminal antibody and lysates from G5824 and G5826 tumor tissues." (PMID 40615663, 2025). "We performed RT–PCR using primers for the exon 2 of PLEKHA1 and the 3’- untranslated regions (UTR) of TACC2 to detect the predicated PLEKHA1-TACC2 transcript in tumor tissue of ESCC 1, followed by Sanger sequencing." (PMID 40615663, 2025). "Specially, FGFR2 rearrangements (FGFR2/VTI1A and FGFR2/TACC2) were recurrently detected in 3.1% (2/64) PC GC tumor samples." (PMID 34551773, 2021). "However, there was few studies to explore the role of 3’-UTR of TACC2 within fusion genes in tumor progression." (PMID 40615663, 2025). "Our previous study revealed inactivation of TACC2 significantly enhance tumor growth in ESCC." (PMID 40615663, 2025). "A total of 359 OC tumor tissues were used to show the correlation between expression of MSI1 and PSI value of TACC2-13336-AP (r = 0.6579, P < 0.0001), TACC2-13333-AP (r = − 0.6554, P < 0.0001)." (PMID 35046435, 2022). "On the molecular level, TACC2 promoted the transcription of the chemokines CCL3 and CCL4 by preventing nuclear translocation and thereby facilitating CD8+ T-cell infiltration into the tumor microenvironment." (PMID 41153795, 2025). "In conclusion, we showed the promising activity of TFDC-based immunotherapy in IDH-WT GBM and the association of low HLA-A expression and the absence of CCDC88A, KRT4, TACC2, and TONSL mutations in tumor cells of patients showing better prognosis." (PMID 37382632, 2023). "Low HLA-A expression and lack of CCDC88A, KRT4, TACC2, and TONSL mutations in tumor cells were correlated with better prognosis." (PMID 37382632, 2023). "Thus, the distribution of TCGA subgroup and primary tumor location was not different according to TACC2-PPAPDC1A status." (PMID 30361512, 2018).